CDH1 (cadherin 1)
Diseases named in the same sentence as CDH1 in open-access papers (continued):
Sharing a sentence is not in itself a finding about the gene and the disease.
tumor (continued). "Expression values of CDH1 in tumor samples were significantly decreased compared to the adjacent normal tissue (**P = 0.0094 normal adjacent tissue vs. tumor tissue M0) suggesting that tumor cells within the samples are losing their adherence capacity and acquire invasive potential." (PMID 29352232, 2018). "A limitation of our analysis of tumor proteomes is that it identifies correlative rather than causal associations; it demonstrates that mutation of CDH1 is associated with reduced expression of other E-cadherin-associated subunits, but it does not demonstrate a causal effect." (PMID 29032073, 2017). "But DAPK promoter methylation had a similar frequency in the blood in GC and controls, these results suggested that promoter methylation of the ten tumor-related genes (p16, CDH1, RUNX3, MLH1, RASSF1A, p15, APC, GSTP1, Reprimo, and MGMT) may be potential biomarkers based-blood test for GC." (PMID 29100425, 2017). "Compared with C-MOs, MAMPCs expressed higher levels of TAM signature genes (i.e., Arg1, Cdh1, Hmox1, Il1r2, Mrc1, and Stab1) that were also highly expressed by MAMs, suggesting that differentiation of C-MOs to MAMPCs (M-MDSCs) is directed toward the tumor-promoting macrophages." (PMID 29387063, 2017). "Therefore, an integrated analysis was performed to evaluate the ability of 11 tumor-related genes (p16, CDH1, RUNX3, MLH1, RASSF1A, p15, APC, DAPK, GSTP1, Reprimo, and MGMT) promoter methylation test using blood samples as a feasible biomarker in GC diagnosis and screening." (PMID 29100425, 2017). "The downregulation of CDH1/E-cadherin expression is considered a hallmark of EMT, and the enrichment of H3K27me3 at the CDH1 promoter has been shown to be a key factor—amongst other gene-repressive mechanisms—in silencing CDH1 expression in many tumor contexts." (PMID 29029452, 2017). "However, it remains largely unknown whether Cdh1 could exert its tumor suppressor role through similarly modulating the E3 ligase activities of other NEDD4 family members, most of which have characterized important roles in tumorigenesis." (PMID 27462441, 2016). "Hence, our finding provided further evidence to demonstrate the putative role for Cdh1 as a tumor suppressor and indicated that reduced expression of Cdh1 in certain types of human cancers might be a biomarker to predict the elevation of PI3K/Akt activities." (PMID 27462441, 2016). "Some of these are: CDH1 that codes for E-cadherin, a transmembrane glycoprotein involved in maintaining epithelial integrity; GATA4 and GATA5 encoding transcription factors; and TFF2 (encoding trefoil factor 2) and FOXD3 (encoding a forkhead box transcriptional regulator) that are tumor suppressors." (PMID 24723914, 2014). "Interestingly, the genes CDH1, ESRP1 and GRHL2 have been shown to play critical roles in epithelial-mesenchymal transition (EMT), a process associated with metastatic events in cancer and also highly relevant to tumor progression." (PMID 23887935, 2013). "Thus, it seems reasonable to presume that aberrant methylation of CDH1 promoter 5′-CpG island may be an early event involved in the pathogenesis of tumor, and is closely correlated with the prognosis of tumor 13–24, 34–37." (PMID 22514028, 2012). "Furthermore, the rate of CDH1 methylation was 63.0% in GC tissues from the patient in stage I/II, which is much lower than that in stage I/II (100.0%) (P < 0.05), it is showed CDH1 methylation may be used in evaluating the malignant degree of the tumor." (PMID 22514028, 2012).
tumor (continued). "The product of CDH1 expression, E-cadherin, mediates the adhesion reaction between the same types of cells and plays a role in the cytoskeleton, implying that the degree of its expression and function directly impact the detachment and re-attachment of tumor cells." (PMID 22514028, 2012). "In this study, we investigated the clinical and molecular significance of piR-823 in OC and explored its potential regulatory role in tumor progression through a proposed epigenetic axis involving PIWIL1, DNMT3B, and CDH1." (PMID 41596471, 2026). "Examination of dabrafenib-treated BrafV600E/+;Rnf43fl/fl;Znrf3fl/fl lesions revealed a reduction in proliferation, mTOR signalling and tumour growth along with an upregulation of GLUL and a decrease in CDH1 and SOX9 levels." (PMID 41261129, 2026). "CDH1 and CDH2 were canonical epithelial and mesenchymal markers, respectively, commonly used to evaluate EMT status and tumor aggressiveness." (PMID 41596471, 2026). "Residing on 16q are many notable tumor suppressor genes including LC3B, CYLD, CDH11, CDH1, ZFHX3, CREB, CTCP, and all metallothioneins (MTs), which emerging research indicates are also tumor suppressors." (PMID 40565600, 2025). "During the metastatic process, the expression of CDH1 decreased while CDH2 increased in malignant tumor epithelial cells, consistent with previous studies that implicate EMT signaling in tumor metastasis." (PMID 41050411, 2025). "We found that genes involved in EMT—CDH1, CDH5, and ZEB1—allowed for the differentiation of healthy cells from tumor samples." (PMID 40332096, 2025). "CDH1 was downregulated when the TP was compared with N, while SNAI2 was downregulated in all tumour regions." (PMID 40869272, 2025). "Studies have shown that overexpression of DNMT1 leads to methylation-mediated silencing of promoter regions of multiple tumor suppressor genes (such as p16, RASSF1A, and CDH1), thereby inhibiting apoptosis and promoting tumor cell proliferation and invasion." (PMID 41394878, 2025). "All PDGCAs expressed markers of tumor epithelial and stem cells (EPCAM, CDH1, KRT18, CA9, CD24, CD133), stromal and extracellular matrix components (COL3A1, COL5A1, DCN, PDGFRA, and PDGFRB), and mesenchymal stem cells (CD73, CD105, CD90)." (PMID 40723172, 2025). "The significance of the CDH1 gene in cancer, particularly in the context of HDGC, lies in its role as a tumor suppressor." (PMID 40585607, 2025). "The maintenance of epithelial integrity during prostate oncogenic transition, tumor start, and progression demonstrates the comprehensive significance of CDH1 (E-cadherin)." (PMID 40693059, 2025). "In many cancer types, both E-cadherin (CDH1) and N-cadherin (CDH2) contribute to tumor behavior, though their functions can diverge depending on tumor type, microenvironment, and disease stage." (PMID 40860670, 2025). "Transcriptomic profiling revealed that PDGCOs_1 expressed elevated levels of tumor epithelial and stem cell markers, such as EPCAM, CDH1, ALDH3A1, CA9, CD24, and CD133." (PMID 40723172, 2025). "While canonical EMT is well-studied in cancer progression, the hEMT state—marked by co-expression of epithelial (e.g., CDH1, IRF6, JUP) and mesenchymal (LAMC2, ITGB4, TGFA) genes—has emerged as a driver that enhances cellular plasticity and tumor metastasis." (PMID 40777467, 2025).
tumor (continued). "When we focused on different expressed genes in a pathway related to tumor development, there were some important oncogenes correlated with JAM2, such as JUN, MMP1, CDH1, and so on." (PMID 39838844, 2025). "RUNX3 has been shown to promote CDH1 expression and inhibit EMT and cell migration, thereby restraining tumor invasion and progression." (PMID 41002582, 2025). "Molecules with tumor suppressor functions such as CAMK2N1, CDH1, IGFBP4, RGS2, and WNT5A were upregulated in MDA231 cells after their co-culture with DBMSCs in an IC setting." (PMID 39768220, 2024). "The genes CDH1, CDH2, and MMP9, which are involved in promoting tumour cell metastasis, was significantly increased in H128-LM cells and H128-BPM cells compared to H128 cells." (PMID 38644473, 2024). "The overexpression of UHRF1 repressed the transcription of such tumor-suppressor genes as CDKN2A, BRCA1, and CDH1 through DNMT1-mediated DNA methylation." (PMID 38725075, 2024). "QRT‐PCR assays confirmed that the epithelial gene Cdh1 was significantly downregulated while the mesenchymal genes, Cdh2, Vim and Fn1, were significantly upregulated in the TMPL tumor organoids compared to the TMP organoids." (PMID 39049720, 2024). "On the other hand, CAF2 lowered the expression of the tumor- and metastasis-suppressor DLC1, as well as CDH1 in estrogen-unstimulated conditions, further indicative of induction of EMT." (PMID 38388711, 2024). "However, studies focusing on CDH1-unaltered ILC are scarce, and several aspects regarding its clinicopathological (age, site, menopausal status, T factor, N factor, and tumor grade) and molecular characteristics (tumor mutational burden and co-mutated genes) remain unknown." (PMID 39201647, 2024). "Consistently, TS3 tumor has higher expression of epithelial CDH1 (coding for E-cadherin) and lower expression of Vimentin compared to the EMT cluster, suggesting TS3 tumor state is largely epithelial in nature despite upregulation of some genes shared in EMT." (PMID 39289380, 2024). "The high expression of tumor-related genes (EPCAM, CD24, CDH1, ELF3, KRT18, KRT19, KRT8, and MUC1) in groups 10 and 11 suggests that cells in these groups are tumor cells." (PMID 38693422, 2024). "The human E-Cadherin gene (CDH1) gene codes for a cell–cell adhesion protein that is essential for epithelial cell differentiation and tumor control." (PMID 38397241, 2024). "SNAI1, CDH1, and FN1 gene expression was detected more frequently in EPCAMlow than in EPCAM-negative primary tumor spots." (PMID 39456890, 2024). "Downplay of E‐cadherin (CDH1) and epithelial–mesenchymal transition (EMT) play critical roles in facilitating tumor invasion and metastasis." (PMID 39619995, 2024). "Several well-known tumor markers for HNSCC were highly expressed in almost every cell cluster, including Keratin 6A (KRT6A), Keratin 14 (KRT14), and Cadherin-1 (CDH1)." (PMID 36982384, 2023). "knockdown of UHRF1 decreased the recruitment of DNMT1 to the CPG islands, thereby decreasing the maintenace of DNA methylation and re-elevating the epigenetic-silenced tumor suppressor genes such as RARB, CDH1, and PSP94." (PMID 36593255, 2023). "SNAI1 induces EMT by binding to the epithelial-tumor suppressing gene CDH1, amongst other epithelial genes, repressing E-cadherin and claudins." (PMID 36980876, 2023). "They act as transcription factors and by binding to the CDH1 gene region—CDH1/PKP2 on chromosome 16, repress the adhesion epithelial genes, such as CDH1 expression, in tumor cells." (PMID 37174083, 2023).
tumor (continued). "There was a significant correlation between the mRNA expression of the EMT (epithelial–mesenchymal transition) markers CDH1 (E-cadherin) and VIM (vimentin) and high CYSLTR1 gene expression in tumor samples." (PMID 36834820, 2023). "CDH1 and VIM gene expression were significantly reduced and increased, respectively, in tumor samples with high CYSLTR1 gene expression." (PMID 36834820, 2023). "The results of transcriptome sequencing after knockdown of SNHG25 in HCT-116 cells showed that the expression of several tumor metastasis-related genes changed significantly (MMP2, VIM and CDH1), among which the expression of MMP2 decreased most." (PMID 37751586, 2023). "The two cancer-related genes displaying the strongest signals of positive selection, cadherin-1 (CDH1) and catalase (CAT), also play roles in tumor development." (PMID 37728212, 2023). "The EZH2 protein mediates modifications in histone methylation that repress several tumor suppressor genes, as DKKI, CDH1, and DAB2IP." (PMID 37404760, 2023). "In contrast, CDH1 and HIF1A levels were negatively correlated with most tumor-infiltrating immune cells." (PMID 37716978, 2023). "On the other hand, CDH1 and VIM expression were higher in tumor samples with high expression of the CYSLTR2 gene." (PMID 36834820, 2023). "The mRNA level of CCL8 in tumor-infiltrating monocytes was also found to be positively correlated with VIM, negatively with cadherin 1 (CDH1), and positively with the metastatic potential of HCC." (PMID 37006233, 2023). "IFITM1 gene was particularly overexpressed in the CDH1-TANGO6 deletion, a feature previously observed in several aggressive tumours, and shown to enhance tumour proliferation and invasion." (PMID 37249750, 2023). "Mutations typically associated with an indolent ER+/luminal A phenotype, such as CDH1 and MAP3K1, were more frequent in MKSlo/ERShi tumours, consistent with previous data." (PMID 37935787, 2023). "This suggested that the sensitivity of CDH1-null cells to the pan AKT inhibitors may be explained more by the inhibition of AKT3 rather than AKT1 and AKT2, and therefore that over-expression of AKT3 represents a vulnerability in tumours deficient in E-cadherin." (PMID 35406381, 2022). "While the mRNA levels of CDH1 decreased, the mRNA level of the FHIT and TTPAL genes increased in the tumor tissues." (PMID 36161592, 2022). "They found that PGK1 that had redistributed to the nucleus induced EMT, via repression of E-cadherin expression, through binding to the core promoter region of CDH1, while cytoplasmic PGK1 supported tumor cell proliferation through its metabolic function." (PMID 35326492, 2022). "Numerous genes that inhibit tumour growth, such as CDKN2B, CDKN2A, CDH1, DAPK1, SOCS1, and SHP1, were rendered inactive as a result of DNA hypermethylation at the CpG islands that are associated with their promoters." (PMID 36359286, 2022). "We added cell line metadata including lineage/tumor type, as well as a feature describing EMT state based on the ratio of CDH1 to VIM expression (see “Methods”)." (PMID 35768873, 2022). "Cdh1-depleted tumor cells, especially TNBC cells, are more sensitive to PARP inhibitors, highlighting the therapeutic potential of combining Cdh1 inhibition and PARPi for TNBC treatment." (PMID 35627188, 2022). "Immunofluorescent, Western Blot, and qPCR showed that C8018‐7840 notably decreased CCL18‐PITPNM3 induced vimentin and recovered CDH1 expression, which further confirmed that C8018‐7840 inhibited PITPNM3 dependent tumor metastasis." (PMID 36285700, 2022). "Alteration of mRNA levels of CDH1, FHIT, PTEN, and TTPAL genes in tumor tissues was determined compared to control tissues." (PMID 36161592, 2022).
tumor (continued). "We analysed the expression of mRNAs for CDH1, PTEN, FHIT, and TTPAL by real-time PCR and observed downregulation of CDH1 and upregulation of FHIT and TTPAL in the tumor tissues." (PMID 36161592, 2022). "From the previous study of our group, the dysregulated proteins AMBP, KLK3, LMAN2, and TTR were found dysregulated in urine and tumor tissue from PCa patients, while SECTM1 was only found in urine from PCa patients, and CDH1 and EFEMP1 were only in PCa tissue." (PMID 35454907, 2022). "Compared to the parent LNCaP cells, expression of AR, AHR, CDH1, CXCR7, FLNA, ITGA6, and UGT2B15 in tumor was significantly inhibited." (PMID 33808801, 2021). "Coincident upregulation of both epithelial and mesenchymal genes was observed in the majority of blood-derived CTC samples compared to primary tumour, while a few epithelial genes such as CLDN7, CD24 and CDH1 were downregulated in the CTC samples." (PMID 34206049, 2021). "Intriguingly, the genes encoding MMS19 and CIA2B-FAM96B both reside in close proximity to tumor suppressor genes (PTEN and CDH1 respectively) that are frequently deleted in cancer, which increases susceptibility to passenger deletion." (PMID 34857765, 2021). "The upregulated MET promotes the downregulation of the epithelial markers of pancreatic cancer cells (FOXA1 and CDH1) and the upregulation of vimentin expression, which eventually promotes the EMT process and increases tumor cell migration." (PMID 33390809, 2021). "They found that VPS4A is essential in cancers with VPS4B loss adjacent to SMAD4 on chromosome 18q, and VPS4B is required in tumours with co‐deletion of VPS4A and CDH1 (E‐cadherin) on chromosome 16q." (PMID 34254730, 2021). "Because our data suggested a potential relationship between MSI2 expression and tumor grade in CRC metastases, we investigated the expression of E-cadherin (CDH1), in relation to MSI2, in 28 randomly chosen patients with mCRC." (PMID 34237057, 2021). "In previous studies, CDH1 and CDH13 were proved as functional tumor inhibitory factors, involved in inhibiting the invasion, proliferation and metastasis of tumor cells." (PMID 33442417, 2021). "The large range of reported CDH1 mutation frequencies (12–85%) may have technical reasons, including different sequencing methods and different pre-processing (DNA sequencing with or without tumor microdissection)." (PMID 34359596, 2021). "Compared with the primary tumor, in the metastasis group, the mesenchymal markers (CDH2, VIM, TWIST1, SNAI1, ZEB1) and ferroptosis drivers increased, and the epithelial marker CDH1 and ferroptosis suppressor decreased." (PMID 35127731, 2021). "Adherens junctions are mainly composed of a transmembrane calcium-dependent glycoprotein named E-cadherin (also known as CDH1), which is considered a tumor suppressor maintaining integrity at local and tissue levels." (PMID 33776764, 2021). "The prognostic risk score was an independent risk factor for the prognosis of GC, which was significantly correlated with N stage and tumor location, positively correlated with the VIM gene, and negatively correlated with the CDH1 gene." (PMID 34745226, 2021). "Ectopic expression of miR-199a-5p in MDA-MB-231 cells inhibited the expression of the EMT-related genes CDH1, ZEB1 and Twist, and elevated levels of miR-199a-5p-impaired cell motility, invasiveness and tumor growth in vivo." (PMID 33572395, 2021). "To characterize NMUR2-positive CRC samples, we analysed the level of CDH1 (E-cadherin), a functional marker of cancer cell differentiation, and MMP1, a mediator of primary tumour invasion, in groups with various NMUR2 expression levels." (PMID 34493299, 2021).